C3 (complement C3)
Diseases named in the same sentence as C3 in open-access papers (continued):
Sharing a sentence is not in itself a finding about the gene and the disease.
Sepsis (78 papers, 2011 to 2026). Sepsis is defined as life-threatening organ dysfunction caused by a dysregulated host response to infection. "Concentrations of complement factors C3, C3a, C3c, C5, C5a, and soluble terminal complement complex were assessed in ethylenediaminetetraacetic acid plasma samples collected within 24 h after sepsis diagnosis using enzyme-linked immunosorbent assays." (PMID 36797757, 2023). "Patients with C3 deficiency frequently develop severe episodes of recurrent pneumonia, meningitis or sepsis." (PMID 22996269, 2013). "Based on our experimental results, extensive lung damages due to severe sepsis were significantly distinct, associated with the exhaustion of complement C3." (PMID 23091606, 2012). "In this study, we investigated the role of complement C3 deposition on anthrax particles for neutrophil recognition of bacterium and/or its cell wall peptidoglycan, an abundant pathogen-associated molecular pattern that supports anthrax sepsis." (PMID 32668703, 2020). "For blocking the central complement component C3 during development of sepsis-caused MODS, clinical trials might be safe but these trials are pending and require a special focus on the benefits or maladies for mental alterations during sepsis." (PMID 30949180, 2019). "Moreover, the recent studies have indicated that the complement depletion, such as C3, C1q and B factor, is strongly associated with the incidence of coagulopathy during sepsis." (PMID 23091606, 2012). "Besides, the strong association between complement C3 depletion and coagulopathy was observed, with a distinct relationship to D-dimer concentration during sepsis." (PMID 23091606, 2012). "Moreover, the exhaustion of complement C3 in late stage of sepsis was associated with significantly decreased defense to pathogenic invasion due to injured T-cell immunity." (PMID 23091606, 2012). "Additionally, platelets may directly participate in complement activation by associating with C3(H2O), thereby further integrating the coagulation and complement systems in the context of sepsis." (PMID 39445002, 2024). "In general, complements C4 and C3 consumption has been observed in septic patients, which is mirrored in the generation of increased levels of complement activation products, including the anaphylatoxins C4a, C3a, and C5a that are associated with severity and mortality in sepsis." (PMID 34903692, 2022). "Diverse insults, including ischemia-reperfusion injury, nephrotoxins, and sepsis, can initiate complement activation, which converges on C3 and C5, fueling inflammatory escalation and tissue injury." (PMID 42253993, 2026). "In clinical studies of severe sepsis, C3 and C4 were reduced because C3 and C4 are degraded and activated to C3a and C4a, respectively." (PMID 40539044, 2025). "Previous studies suggested a correlation between the complement C3 level and disease progression and prognosis in pediatric sepsis, and this is supported by our preliminary findings." (PMID 41291834, 2025). "RT-qPCR analysis confirmed significant upregulation of Mt1, Mt2, Saa3, and C3 across all microvascular compartments following sepsis." (PMID 40892345, 2025). "In Astrocyte 1, inflammation-associated genes (GFAP, FOS, C3, CD74) were significantly upregulated, while BBB-related genes (GRIA2, NRGN, TXNIP) were downregulated in sepsis." (PMID 41030458, 2025). "In summation, complement proteins C3 and C5 are pivotal in the onset and progression of sepsis, highlighting the critical connection that inflammasome activation represents between the complement system and coagulation pathways." (PMID 39445002, 2024). "The results of this study point toward profound activation of the complement pathway in sepsis patients, reflected by a decrease in complement components C3 and C5 and an increase in C3a, C3c, C5a, as well as the end product sTCC." (PMID 36797757, 2023). "It has been shown that astrocytes in an animal model of lipopolysaccharide-induced sepsis increased expression of C3." (PMID 37483351, 2023).
Sepsis (continued). "A baboon model with E. coli-induced sepsis showed that C3 inhibition by compstatin reduced platelet aggregation, similar to our in vitro model." (PMID 36591264, 2022). "Still, complement overrepresentation is not completely explained by population stratification, as when African American children with severe sepsis are compared to African gnomAD participants, C3 c.443G > A and CFH c.2850G > T remained overrepresented." (PMID 34973142, 2022). "In a prospective pilot study of markers of complement activation in sepsis, higher C4d (3.5-fold), factor Bb (6.1-fold), C3 (0.8-fold), C3a (11.6-fold), and C5a (1.8-fold) levels were seen compared with healthy volunteer controls." (PMID 34991675, 2022). "When treated with lipopolysaccharides (LPS), a bacterial endotoxin that mimics infection and sepsis, the mice developed albuminuria, kidney function impairment, and C3 glomerular deposition at levels comparable with the wild-type mice." (PMID 34149444, 2021). "An increased C3 and C4 consumption in sepsis, found by inversely lower C3 and C4 levels in patient plasma, is more often associated with unfavorable outcome." (PMID 34396466, 2021). "In line, deposition of immune complexes along with C3 has been suggested in one human autopsy study as a pathomechanism of sepsis-induced multiple organ failure including the lungs." (PMID 34191093, 2021). "In the same sepsis model, systemic blockade of C3 by compstatin also revealed organ protection on multiple levels." (PMID 30949180, 2019). "Concerning complement, pre-pro-complement C3 was highly expressed in all organs except in the brain during the whole course of sepsis." (PMID 30949180, 2019). "This is in line with previous findings that treatment with hFH decreased bacterial clearance from blood due to reduced pneumococcal C3 opsonization in a murine sepsis model." (PMID 31883521, 2019). "In bacterial infections and sepsis, complement proteins act on the surface of microorganisms by interacting with a complement protein 3 (C3) fragment, which plays an integral role in the process of phagocytosis of microorganisms." (PMID 31671729, 2019). "Our previous studies have found that complement C3 exhaustion due to severe sepsis would deteriorate immunity and coagulopathy meanwhile." (PMID 29062836, 2017). "In human sepsis, circulating complement C3 concentrations are decreased, though C3 is described as a positive acute phase reactant." (PMID 25699043, 2015). "In severe sepsis, significantly lower levels of plasma C3 have been reported and a failure of PBLs to induce defensins ex vivo in response to endotoxins." (PMID 25646095, 2014). "Targeting C3 or its activation products especially C3b in the setting of sepsis, unless very carefully regulated, has the potential to depress the opsonic system, which is vital for the in vivo response to bacteria in the setting of sepsis." (PMID 22482043, 2012). "These investigators argued that changes in C3 levels during severe sepsis were more consistent with protective host defense functions but did not support a role for C3 in the pathogenesis of acute fulminant clinical sepsis." (PMID 23049598, 2012). "The complement depletion, which included C3 and C4 depletion, was almost impossible to recover back to normal once it occurred in the early phase of sepsis." (PMID 23091606, 2012). "Given the correlations between these lipids and immune cells, we hypothesize that the pathogenesis of severe sepsis in the elderly may be related to reductions in complement C3, complement C4, monocytes, and CD8+ T cells." (PMID 41346598, 2025). "Our findings reveal markers of the microvascular response to sepsis, which include increased levels of HP, C3, Chil3/CHI3L1, and MMP8, both at the transcriptomic level in mouse and human kidney microvasculature and at the protein level in circulating plasma of SA-AKI patients." (PMID 40892345, 2025).
Sepsis (continued). "Levels of complement C3 and C4 may decrease in patients with sepsis, and their reduction is associated with the development of acute kidney injury (AKI) in sepsis." (PMID 39445002, 2024). "Complement C3 inhibition by compstatin decreased early fibrogenic events in sepsis-induced ARDS in baboons, suggesting that inhibiting complement could be a potential strategy for preventing pulmonary fibrosis in ARDS patients." (PMID 37006238, 2023). "Had sepsis been the underlying reason behind astrocytic phenotypic changes, we would have detected changes in C3 expression, which was not the case." (PMID 37483351, 2023). "In contrast to that, in baboons being exposed to E. coli, the reduction in mean systolic arterial pressure (as sepsis sign) was greatly improved among other organ functions by blockade of C3 by compstatin even when applied in a delayed fashion up to 5 h post-infection." (PMID 34191093, 2021). "Interestingly, during sepsis, C3 proteolysis is predictive of the severity of infection and sepsis can result in MI45,46." (PMID 30992428, 2019). "Other products derived from activation of the complement system play an important role in sepsis, such as C3b (from C3), which is a key opsonisation factor that reacts with phagocytes receptors to favour internalization of bacteria and their subsequent elimination." (PMID 27239102, 2016). "Moreover, systemic infections like sepsis were found to activate complement, consuming C3 and C4 and generating enhanced levels of C3a and C4a especially in patients succumbing to sepsis." (PMID 26303896, 2015). "Thus, C5 is a particularly interesting target for intervention in sepsis, leaving C3 free to opsonize in microbial defense." (PMID 26612199, 2015). "In support of a functional role for C3 in thrombosis, in a baboon model of sepsis-induced thrombosis, the C3 inhibitor compstatin, which binds to C3 and inhibits cleavage of C3 by C3 convertase complexes, resulted in reduced TF and PAI-1 expression and decreased microvascular thrombosis." (PMID 24278688, 2012). "Similarly, our study shows that C3, a component of the complement system and has a well-described role in sepsis, is consistently upregulated across renal microvascular compartments in both mice and humans, suggesting a conserved role in endothelial activation during SA-AKI." (PMID 40892345, 2025). "Using RT-qPCR, we confirmed the upregulation of HP, C3, Chil3/CHI3L1, and MMP8 in renal microvascular compartments in both CLP-sepsis mice and human post-mortem kidney biopsies from patients with SA-AKI." (PMID 40892345, 2025). "Dot plot visualization further confirmed these trends at the gene level, with C3, SERPING1, and HLA-A/B/C being notably upregulated in Astrocyte 2 under sepsis conditions, while EMP1, CLCF1, and PTGS2—representing A2 features—were similarly elevated." (PMID 41030458, 2025). "We aimed to investigate associations between the key molecules in the terminal complement pathway, C3, C3a, C3c, C5, C5a, and soluble TCC (sTCC), and the dysregulated immune response in sepsis patients." (PMID 36797757, 2023). "For example, the outgoing signaling of C1_CD36, C3_B, C9_STOM, and C10_ULK1 cells was dominated by “pattern 1,” which included RESISTIN and VISFATIN in sepsis." (PMID 37919720, 2023). "The effectiveness of the complement inhibition therapies at the C3 level (compstatin) and C5 level (RA101295), along with CD14 inhibition monotherapy were already proven to be beneficial in porcine and baboon sepsis models." (PMID 36059503, 2022). "High C3, MAC, and MBL serum concentrations are predictive for sepsis-induced disseminated intravascular coagulation." (PMID 34396466, 2021). "Except for immunoglobulin M (IgM) levels, the levels of immunoglobulin A (IgA), immunoglobulin G (IgG), complement C3, and C4 were higher in SARS-CoV-2 sepsis patients." (PMID 33329592, 2020).
Sepsis (continued). "As sepsis progresses, complement activation by considerable release of cytokines (TNF-α, IL-6, IL-10, etc.)produced enormous components, such as C3a, C4a, and C5a, and further consumed the pool of complement C3 and C4." (PMID 23091606, 2012). "Upregulation of HP, C3, Chil3/CHI3L1, and MMP8 in renal microvascular compartments of both mice and humans may reflect endothelial activation in sepsis, as supported by prior transcriptomic and proteomic studies." (PMID 40892345, 2025). "In line with this, genetic absence of C3 leads to signs of pulmonary injury and multiple organ injury, and general outcome during sepsis is much worse than in wildtype littermates indicating overall protective effects of C3 in case of early bacterial sepsis." (PMID 34191093, 2021). "The three pathways of complement activation converge on component C3, which proceeds to activate complement component 5 (C5), generating C5a and the final, terminal C5b-9 complement complex (TCC) and C5a has a documented, harmful role in sepsis." (PMID 26612199, 2015). "It is interesting to note that some investigations did not conclude that C3 activation was detrimental in the development of severe sepsis." (PMID 23049598, 2012). "In this prospective study, we stratified enrolled sepsis patients into two main groups based on baseline levels of complement C3, rather than conventional APACHE II score." (PMID 23091606, 2012). "Therefore, HP, C3, Chil3/CHI3L1, and MMP8 have established roles in immune modulation, inflammation, and the oxidative stress response, and our study demonstrates their upregulation as part of the endothelial activation signature in sepsis." (PMID 40892345, 2025). "Furthermore, in a recently reported prospective study of severe sepsis and septic shock, the complement system was markedly activated, with significantly decreased C3 and C5 while significantly increased C3a and C5a, although CH50 was not measured." (PMID 40539044, 2025). "However, whereas in the development of glomerulonephritis, C3 deposition can be a crucial part of the pathophysiological process, in the case of trauma and sepsis, this does not appear to be a leading mechanism." (PMID 37542608, 2023). "Activation of the complement cascade (components C3 and C5) was detected in the kidneys in our sepsis patients, but could not be detected in any other tissue." (PMID 37731199, 2023). "However, we also found that CRP was not sensitive as PCT in accordance with complement C3 consumption, which may indicate the important role of complement in late stage of severe sepsis." (PMID 23091606, 2012). "Moreover, we found differences in the levels of IgM, complement C3 and C4 between bacterial sepsis survivors and nonsurvivors, while there only differences in complement C4 levels between SARS-CoV-2 sepsis survivors and nonsurvivors." (PMID 33329592, 2020).
Obesity (69 papers, 2010 to 2026). Accumulation of substantial excess body fat. "C3 activation marker C3a is associated with hepatic steatosis and hepatocyte injury in individuals with severe obesity." (PMID 40422243, 2025). "Increased circulating C3a, a product of the proteolytic cleavage of C3, combined with obesity was associated with a high incidence of PE." (PMID 32971873, 2020). "Elevated circulating concentrations of C3, an acute-phase response protein with a central role in the innate immune system, have been associated with obesity and increased cardiometabolic risk." (PMID 29020958, 2017). "Obesity associated markers - Only Complement C3 showed a significant difference between the lean control group and all three other groups." (PMID 25415563, 2014). "In addition, we found an association between serum adiponectin, which is a marker of obesity and insulin resistance, with serum exosomes C3 levels in GDM pregnancies." (PMID 36080270, 2022). "High serum C3 and plasma CP enzyme levels have been associated with obesity." (PMID 33672392, 2021). "Serum complement C3 levels are closely associated with obesity and related metabolic disorders." (PMID 27029598, 2016). "Similarly, obesity/metabolic dysfunction is associated not only with increased circulating C3, but also C3 cleavage products, such as C3a/C3adesArg." (PMID 24743347, 2014). "The central component of the complement system, C3, is associated with obesity, metabolic syndrome and cardiovascular disease however the underlying reasons are unknown." (PMID 24743347, 2014). "In the present study we evaluated gene expression of complement C3 and C3aR in omental and subcutaneous adipose tissue and plasma C3a/C3adesArg levels in Caucasian women, and their association with anthropometric and biochemical variables over a wide range of degrees of obesity." (PMID 24743347, 2014). "Along with FD, other alternative CS components, such as C3, factor B, factor H, factor I, and properdin, are overexpressed in ATs, which increase with BMI and obesity status." (PMID 40904461, 2025). "The complement system is a key part of liver homeostasis, and C3 has been found to promote hepatic steatosis and obesity-related inflammation." (PMID 40422243, 2025). "Baseline C3 levels and level changes correlated with HOMA, multiple organ IR and T2DM independently of obesity, metabolism- and inflammation-related risk factors." (PMID 39635529, 2024). "In most rodent models of obesity, decreases in FD levels, induction of C1q, and inconsistency in overproduction and secretion of C3 or FB by adipose tissue were seen." (PMID 39635529, 2024). "Both CRP and C3 are acute phase reactants mainly produced in the liver, though in obesity, the excess of these proinflammatory cytokines will promote an increased synthesis of CRP and C3 in adipose tissue." (PMID 39061938, 2024). "Complement 3 (C3) serum levels are considered a pro-inflammatory biomarker for insulin resistance in obesity, and in our study, C3 serum levels exhibited a decreasing trend overall." (PMID 38375199, 2024). "Other studies have linked obesity and weight change with CRP, APCS, ADIPOQ, C3 and other complement proteins, ORM1, and ORM222,34,36–38." (PMID 37794065, 2023). "To further establish the role of complement activation in MAT expansion, we analyzed C3 KO mice subjected to HFD to induce obesity followed by Rosi treatment." (PMID 34155972, 2021). "Various proteins were identified in all groups of patients, but changed levels of fibrinogen complement C4 and C3 were a common element found in groups burdened with obesity and poor metabolic control." (PMID 33668851, 2021). "The groups burdened with complications, obesity, and poor metabolic control were characterized by increased levels of fibrinogen, complement C4 and C3." (PMID 33668851, 2021).